ALK (ALK receptor tyrosine kinase)
Diseases named in the same sentence as ALK in open-access papers (continued):
Sharing a sentence is not in itself a finding about the gene and the disease.
lung adenocarcinoma (continued). "Several other driver molecular alterations have been identified in lung adenocarcinoma, including somatic mutations of KRAS, BRAF, STK11, DDR2 and members of the FGFR family, as well as ALK rearrangements." (PMID 24236184, 2013). "In contrast, according to a study including EGFR wild-type and advanced-stage lung adenocarcinoma patients who received either monotherapy or platinum-doublet chemotherapy, ALK positivity conferred superior overall survival." (PMID 27234388, 2013). "In conclusion, ALK-rearranged lung adenocarcinoma exhibited distinct clinicopathological and morphological features compared with other genotypes." (PMID 24194854, 2013). "Patients with ALK-positive lung adenocarcinoma were younger at diagnosis and had a higher stage, most commonly at stage IV." (PMID 23741400, 2013). "We have revealed that ALK fusion-positive tumours constituted a particular subset in lung adenocarcinomas in terms of clinical characteristics, histology and etiology, as well as molecular changes." (PMID 23289484, 2013). "The presence of anaplastic lymphoma kinase (ALK) gene rearrangement in lung adenocarcinomas is the best predictor of response to crizotinib, an ALK tyrosine kinase inhibitor." (PMID 24194854, 2013). "The FISH technique is actually standardized at prognostic and predictive level in the evaluation of the Her-2/gene in breast and gastric cancer, ALK gene in lung adenocarcinoma, 1p/19q in oligodendroglioma and in several gene rearrangements in lymphoma." (PMID 23874541, 2013). "For lung adenocarcinoma, EGFR mutation and ALK rearrangement testing is recommended, KRAS mutation testing is suggested by the NCCN guidelines." (PMID 27605195, 2013). "KRAS mutations are reported in 15–25% of patients with lung adenocarcinoma and are typically mutually exclusive with EGFR mutations or ALK gene rearrangements." (PMID 25562798, 2012). "In addition to EGFR mutations and ALK rearrangements, genomic studies have also identified frequent copy number changes and somatic mutations affecting components of key signaling pathways in adenocarcinoma of the lung including KRAS, Her2, BRAF, C-MET, MEK1 and PIK3CA." (PMID 25562798, 2012). "Until today, several biological events have been identified in lung adenocarcinoma, including epidermal growth factor receptor (EGFR) mutations and anaplastic lymphoma kinase (ALK) translocations, offering new hopes to patients with metastatic disease." (PMID 27398239, 2012). "In fact, using high-sensitivity anti-ALK immunohistochemistry (iAEP method) as screening, we have identified several novel ALK fusions in various types of cancers including lung adenocarcinoma, lymphoma, sarcoma, and renal cell carcinoma." (PMID 22347464, 2012). "Major recurrent mutations in lung adenocarcinoma have been found to occur in EGFR, KRAS, HER2, BRAF, ALK and ROS1." (PMID 22140546, 2011). "ALK is also among the kinases that gain activity in lung adenocarcinomas, lung carcinoid tumors and squamous cell lung carcinomas in comparison to healthy lung." (PMID 21151926, 2010). "This case report details the management of a 33-year-old male never-smoker diagnosed with stage III lung adenocarcinoma harboring an Echinoderm microtubule-associated protein-like 4 (EML4)-anaplastic lymphoma kinase (ALK) fusion gene." (PMID 41293380, 2025). "In conclusion, our preliminary study demonstrated that radiomics signature derived from pretreatment CT can serve as a non-invasive biomarker for predicting BM in patients with stage III/IV ALK-positive lung adenocarcinoma, backed by an independent external test dataset." (PMID 40606995, 2025). "Moreover, ALK-positive lung adenocarcinoma samples are clinically scarce, making it difficult to meet the demand for an adequate supply of controls." (PMID 40017673, 2025).
lung adenocarcinoma (continued). "Although prior studies suggest a low K-ras mutation rate in GGO-dominant lung adenocarcinoma and mutual exclusivity between EGFR/ALK and K-ras alterations, future research should expand genetic profiling to assess the impact of multi-gene interactions on CT imaging features." (PMID 41020204, 2025). "A novel automated solution for ALK IHC quality control management was investigated by comparison with the established D5F3 antibody on the VENTANA system in 87 lung adenocarcinoma specimens with known ALK status re-analyzed by fluorescence in situ hybridization." (PMID 40017673, 2025). "In NSCLC, ALK gene rearrangements are usually detected in lung adenocarcinoma." (PMID 40052122, 2025). "Our study showed that ALK-rearranged lung adenocarcinomas exhibit downregulation of PD-L1 and HLA-I, which may contribute to the limited efficacy of PD-1/PD-L1 inhibitors in this population." (PMID 40376302, 2025). "Further analysis of the qualitative and quantitative parameters of three-dimensional CT in patients with different EGFR and ALK gene rearrangements revealed that the BS, PIS, VBS, MND, NV, ACTV, and SCP were correlated with EGFR mutation in GGO-associated lung adenocarcinoma." (PMID 41020204, 2025). "A 59-year-old male, a patient of ALK+ lung adenocarcinoma demonstrating excellent initial response to targeted therapy with ALK inhibitor ceritinib, developed prostatic adenocarcinoma with neuroendocrine differentiation 36 months later, which was treated with abiraterone and leuprolide." (PMID 42077583, 2025). "Compared to EGFR gene mutations, ALK rearrangement is more likely to occur in younger, non-smoking or light-smoking lung adenocarcinoma patients." (PMID 41378298, 2025). "ALK rearrangements occur in approximately 3–10% of NSCLC patients, and echinoderm microtubule-associated protein-like 4 (EML4) is the most common ALK fusion partner in lung adenocarcinoma." (PMID 40052122, 2025). "Genetic alterations in key oncogenes have been frequently identified in lung adenocarcinoma (LUAD), including genes encoding epidermal growth factor receptor (EGFR), Kirsten rat sarcoma viral oncogene homolog (KRAS), and anaplastic lymphoma kinase (ALK)." (PMID 40621945, 2025). "In addition, a patient with lung adenocarcinoma concomitant EGFR mutations and EML4-ALK fusion benefited from combination treatment with EGFR-TKIs and ALK-TKIs." (PMID 40052122, 2025). "Here, we present a case with lung adenocarcinoma (LUAD) harboring an ALK rearrangement." (PMID 38699646, 2024). "Therefore, directly comparing ROS1+ lung adenocarcinomas with ALK+ or RET+ tumors, while excluding cell lines, provides further insights into the tumor microenvironment." (PMID 39737401, 2024). "Previous study suggested that females and never smokers with lung adenocarcinoma are more likely to harbor EGFR/ALK/ROS1 mutation." (PMID 39000058, 2024). "We first utilized TCGA never-smoker lung adenocarcinomas without EGFR or ALK driver mutations (n = 46)." (PMID 39300154, 2024). "Our initial analysis specifically focused on 69 lung adenocarcinoma (LUAD) cell lines without oncogenic EGFR/ALK mutations." (PMID 39300154, 2024). "Exploring whether this mechanism similarly contributes to lung adenocarcinoma could open new therapeutic avenues, particularly for combined treatment strategies with ALK and STAT3 inhibitors." (PMID 39555099, 2024). "In lung adenocarcinoma, PTK7 was found to be overexpressed in cancer tissues compared to normal lung tissues, and the positivity of PTK7 expression was higher in cases with ALK mutations and lower in cases with EGFR mutations." (PMID 39474113, 2024). "We report here one case with ALK-positive lung adenocarcinoma in which the patient achieved a prolonged progression-free survival (PFS) of 97 months after undergoing precise pleural effusion NGS and receiving combined bevacizumab treatment following multiple-line ALK-TKI resistance." (PMID 38978737, 2024).
lung adenocarcinoma (continued). "The importance of EML4-ALK fusion protein, expressed in 2–9% of lung adenocarcinomas, has led to the recommendation of ALK testing in non-squamous histology if EGFR mutations are not detected." (PMID 38396722, 2024). "Given that both LCNEC and ALK-positive lung adenocarcinoma may present with multiple BMs, surgical resection alone can only confirm the diagnosis of a single tumor and is too invasive, while whole-brain radiotherapy is indicated only for palliative care." (PMID 39723252, 2024). "The scarcity of proteogenomic research on lung adenocarcinoma in never smokers without EGFR or ALK mutations has resulted in an oversimplified view of these diseases, treating them collectively as a single, homogeneous, yet undefined entity." (PMID 39300154, 2024). "In our recent study concerning patients with stage I and II lung adenocarcinoma, who exhibit clinical node negativity, we have discovered intriguing connections between certain genomic features, such as ALK rearrangements, and the prediction of unexpected nodal metastasis." (PMID 38023117, 2023). "This study investigated the association of contrast-enhanced Computed Tomography (CT) radiomic features of lung adenocarcinoma lesions, alone or integrated with clinical parameters, with tumor mutational status (EGFR, KRAS, ALK alterations) and Overall Survival (OS)." (PMID 37760521, 2023). "Immunohistochemical characterization of six tumor regions was done for ALK and markers of lung adenocarcinoma (NKX2.1), epithelial (E‐cadherin, pan‐cytokeratin, and cytokeratin 18) and mesenchymal (vimentin) phenotypes, tumor vasculature (CD31), and basement membrane organization (collagen type IV)." (PMID 36423211, 2023). "The current case report describes a 71-year-old woman with overlapping anaplastic lymphoma kinase (ALK)-rearranged lung adenocarcinoma and HER2-mutant breast cancer, who achieved improvement with concurrent use of the molecularly targeted agents Alectinib, Trastuzumab, and Pertuzumab." (PMID 37113357, 2023). "In some series, the cancer type was not a significant variable, while in others, renal and lung adenocarcinoma histology have been identified as risk factors; in particular, ALK+ and EGFR+ lesions were associated with higher rates." (PMID 37046755, 2023). "According to one Korean dataset, there were four patients (1.8%) with a BRAF mutation among 222 Stage III/IV lung adenocarcinoma patients without EGFR/ALK aberrations." (PMID 37374289, 2023). "The tyrosine kinase inhibitors (TKIs) of EGFR and ALK have been proven remarkably beneficial in bringing a better clinical outcome in patients with lung adenocarcinoma in both adjuvant or salvage settings, whose impact upon the observation of PORT efficacy was not considered by these RCTs." (PMID 37188197, 2023). "Four patients with lung adenocarcinoma (LUAD) who carried no EGFR/ALK mutations histologically evolved into SCLC." (PMID 38022621, 2023). "Of these, EGFR mutation occurs in 55% of Asian patients and 15% of non-Asian patients with lung adenocarcinoma, followed by ALK rearrangement occurs in 5–8%, and other mutations are limited to 5% of non-squamous NSCLC." (PMID 37789413, 2023). "Meanwhile, the association of smoking and ALK-TKIs on OS of treatment-naïve ALK-positive advanced lung adenocarcinoma patients in the real world remains unclear." (PMID 37007097, 2023). "Moreover, the therapeutic dividend attributed to anaplastic lymphoma kinase (ALK) inhibitors (e.g., crizotinib, ceritinib, alectinib, and brigatinib) is confined to individuals harboring lung adenocarcinomas bearing the ALK fusions." (PMID 37686123, 2023). "A total of 52 patients with ALK-rearranged lung adenocarcinoma were enrolled in this study." (PMID 37371571, 2023). "The association of smoking and ALK-tyrosine kinase inhibitors (TKIs) on overall survival (OS) of treatment-naïve ALK-positive advanced lung adenocarcinoma remains unclear in real-world." (PMID 37007097, 2023).
lung adenocarcinoma (continued). "Here, we investigated the potential biomarker utility of circulating cytokines vis-à-vis ctDNA in ALK-rearranged+ lung adenocarcinoma (ALK + NSCLC) and explored the optimal combination of molecular parameters that could indicate disease progression." (PMID 37120670, 2023). "Testing lung adenocarcinomas for ALK rearrangements has become standard practice since remarkable responses in ALK rearrangement-positive NSCLC patients treated with oral TKIs (i.e., alectinib, brigatinib, ceritinib, crizotinib, lorlatinib) have been documented." (PMID 36230877, 2022). "Anaplastic lymphoma kinase (ALK) fusions drive ∼5% of lung adenocarcinomas." (PMID 36207130, 2022). "ALK fusions were identified in four patients (3%), all with lung adenocarcinoma." (PMID 35108331, 2022). "In this case report, we identified a novel nonreciprocal ALK fusion, namely, junctional sarcoplasmic reticulum protein 1 (JSRP1) intergenic region-ALK fusion (Jintergenic: A20) via next-generation sequencing in a female patient initially diagnosed with stage IV B lung adenocarcinoma." (PMID 36267987, 2022). "Here, EGFR/ALK-wild type lung adenocarcinoma was set as the reference for comparison." (PMID 35980949, 2022). "In addition, the NGS assay provides a reliable diagnostic tool for the detection of novel fusion partner genes for ALK-rearranged in patients with lung adenocarcinoma." (PMID 35144623, 2022). "A retrospective study including 309 patients with resected stage IA lung adenocarcinoma showed that ALK fusion was associated with a higher risk of disease and more frequent recurrence in regional lymph nodes than ALK-negative tumours." (PMID 35454856, 2022). "Finally, the patient was diagnosed with stage IV ALK-positive advanced lung adenocarcinoma with metastatic malignancy in the right adrenal gland." (PMID 36523965, 2022). "For example, a combination of CT imaging parameters and clinical features can provide therapeutic benefits by identifying genotypic information about anaplastic lymphoma kinase (ALK) for deciding the use of crizotinib for therapy in patients with lung adenocarcinoma." (PMID 36012657, 2022). "Therefore, existing guidelines recommend genetic testing for lung adenocarcinoma patients before treatment, such as EGFR mutations and anaplastic lymphoma kinase (ALK) fusion mutations." (PMID 35692818, 2022). "Although neuroendocrine transformation has been widely observed in EGFRm lung adenocarcinomas, it is not unique, and has been observed in patients with driver mutations in ALK and ROS1." (PMID 35268520, 2022). "Here, we report a case of a patient with metastatic ALK-positive lung adenocarcinoma with an impressive resistance to sequential treatment with ALK TKIs mediated by YES1 and MYC amplification in a contest of epithelial-to-mesenchymal transition and high progressive chromosomal instability." (PMID 35199053, 2022). "In conclusion, this study suggests that EGFR mutations were more likely to occur in non‐smoking, stage III–IV, and female patients with lung adenocarcinoma, whereas ALK&ROS1 gene rearrangements were more likely to occur in young patients with lung adenocarcinoma." (PMID 35081265, 2022). "However, she was recently diagnosed with anaplastic lymphoma kinase (ALK)-positive lung adenocarcinoma." (PMID 33810548, 2021). "Even though most patients with ALK rearranged lung adenocarcinoma have obtained benefits from TKIs, such as crizotinib, the long‐term prognosis may not be as satisfactory due to the emergence of acquired resistance." (PMID 34596344, 2021). "The aim of the study was to provide a reference for further research on the studies of ALK rearranged lung adenocarcinoma and verify whether after complete resection these patients can benefit from targeted drugs." (PMID 34596344, 2021). "Here, we aimed to investigate the clinical characteristics and outcomes of lung adenocarcinoma patients with ALK rearrangement, and analyze whether these patients benefited from targeted therapy." (PMID 34596344, 2021).
lung adenocarcinoma (continued). "Other than stage I, patients with surgically‐resected ALK‐positive lung adenocarcinoma may benefit from targeted therapy." (PMID 34596344, 2021). "The patient was diagnosed with ALK-positive lung adenocarcinoma (cT3N3M1b: stage IVA)." (PMID 34596160, 2021). "The ALK gene rearrangement is observed in 3–5% of adenocarcinomas of the lung, and, hence, identifying patients with ALK aberrations who might benefit from the kinase inhibitor treatment is critical for effective NSCLC treatment." (PMID 34066104, 2021). "In several different cancers, TPR is present through fusion genes, which is formed by coiled-coil motif in TPR with some kinase partner genes such as MET (gastric cancer), NTRK1 (thyroid carcinoma), FGFR1 (myeloproliferative syndromes), and ALK (lung adenocarcinoma)." (PMID 34722501, 2021). "We also compared whether the use of targeted drugs affected survival outcome of ALK rearranged lung adenocarcinoma patients." (PMID 34596344, 2021). "Furthermore, research has revealed that some patients with lung adenocarcinoma have ALK rearrangement, resulting in the EML4–ALK fusion gene product." (PMID 35127511, 2021). "Of special interest, this ratio increased to 5–7% for lung adenocarcinoma patients without EGFR/KRAS/BRAF/ALK mutations." (PMID 32677962, 2020). "ALK rearrangement is most commonly seen in lung adenocarcinoma." (PMID 33352665, 2020). "Therefore, we compared the efficacies of ICIs for the treatment of lung adenocarcinoma with ALK rearrangement and other oncogene drivers, including EGFR mutations." (PMID 32283823, 2020). "To address whether NHERF1 expression could be a consequence upon the activation of ALK signaling, we conducted laboratory experiment in H3122 cells, which is known as a commonly used ALK-positive and crizotinib-sensitive lung adenocarcinoma cell line." (PMID 32164629, 2020). "Besides, ALK fusions were firstly identified in 2007 and occurred in approximately 3–7% of all lung adenocarcinoma patients, and the most common form was echinoderm microtubule-associated protein-like 4/anaplastic lymphoma kinase (EML4-ALK)." (PMID 32677962, 2020). "In this study, patients with MPLAs had a slightly higher ALK-positive rate (17.0%), which may be due to ALK positivity being more frequently found in advanced lung adenocarcinoma." (PMID 32690092, 2020). "Therefore, the purpose of our study was to investigate the differences in CT characteristics and disease spread patterns between patients with lung adenocarcinoma who have ROS1 rearrangement and those with EGFR mutations or ALK rearrangement." (PMID 33005033, 2020). "ALK gene rearrangements often mean that patients may be benefit from ALK‐TKIs treatment, which is glad tidings, especially for those with stage IV lung adenocarcinoma." (PMID 31489711, 2020). "Chromosomal translocations such as those including the ALK gene are demonstrated in anaplastic lymphoma, lung adenocarcinoma, and myofibroblastic tumors, and the translocation EWSR1-CREB1 in tumors as different as clear cell sarcoma and angiomatoid fibrous histiocytoma." (PMID 31970428, 2020). "In addition, we targeted ALK in the EML4-ALK fusion oncogene in the H3122 cell line model for human lung adenocarcinoma." (PMID 33255340, 2020). "Among the clinical features, smoking history was the most powerful factor to differentiate ALK mutated lung adenocarcinomas from the non-ALK mutated ones." (PMID 32266148, 2020). "Lung adenocarcinoma harbours numerous molecular abnormalities, including mutation of the epidermal growth factor (EGF), rearrangement of the gene for anaplastic lymphoma kinase (ALK), and mutations for Kirsten rat sarcoma viral oncogene homologue (KRAS)." (PMID 33425389, 2020). "Histologically, previous studies reported more ALK fusions in patients with lung adenocarcinoma." (PMID 32460789, 2020).